HOXA11 (homeobox A11)
Diseases named in the same sentence as HOXA11 in open-access papers (continued):
Sharing a sentence is not in itself a finding about the gene and the disease.
HOXA11 also shares sentences with these, for which no sentence is quoted: liver cancer (4 papers); adenocarcinoma (2); bladder cancer (2); renal carcinoma (2); acute myeloid leukemia (1); adrenal tumour (1); basal cell carcinoma (1); bone marrow failure syndrome (1); endometritis (1); hand-foot-genital syndrome (1); hemangioblastoma (1); hepatocellular carcinoma (1); infection (1); injury (1); juvenile myelomonocytic leukemia (1); kidney damage (1); kidney diseases (1); laryngeal squamous cell carcinoma (1); liver fibrosis (1); myelogenous leukaemia (1); oral squamous cell carcinoma (1); pregnancy (1); Primary amenorrhea (1); primitive neuroectodermal tumor (1); prostate carcinoma (1); Short stature (1); steatosis (1); urothelial bladder cancer (1); Weaver syndrome (1).